MCM2 (minichromosome maintenance complex component 2)
Diseases named in the same sentence as MCM2 in open-access papers (continued):
Sharing a sentence is not in itself a finding about the gene and the disease.
leiomyosarcoma (2 papers, 2021 to 2023). An uncommon, aggressive malignant smooth muscle neoplasm, usually occurring in post-menopausal women. "Especially, the expression of MCM2 is significantly upregulated in uterine leiomyosarcoma compared to normal myometrium and uterine leiomyoma." (PMID 38066476, 2023). "The fold change of MCM2 in patients with pleomorphic liposarcoma, myxofibrosarcoma, leiomyosarcoma, myxoid/round cell liposarcoma and dedifferentiated liposarcoma was 3.538, 3.819, 4.437, 3.012, and 2.539, respectively." (PMID 34239894, 2021). "Using datasets of Detwiller Sarcoma, MCM2 was also found to be overexpressed in leiomyosarcoma (fold change = 7.904), fibrosarcoma (fold change = 4.867) and malignant fibrous histiocytoma (fold change = 4.180) compared with normal samples." (PMID 34239894, 2021).
leukemia (2 papers, 2012 to 2021). A malignant (clonal) hematologic disorder, involving hematopoietic stem cells and characterized by the presence of primitive or atypical myeloid or lymphoid cells in the bone marrow and the blood. "PCNA and MCM2 levels had a downward trend in xenograft leukemia from sample B-01-Dx." (PMID 33722259, 2021). "Furthermore, simultaneous treatment with FLV and doxorubicin extended the survival of SCID mice bearing 8047 leukemia cells expressing high levels of MCM2." (PMID 22768239, 2012).
liposarcoma (2 papers, 2021 to 2025). A usually painless malignant tumor that arises from adipose tissue. "Another study found that Minichromosome Maintenance Complex Component 2 (MCM2) is upregulated in liposarcoma tissues and cells, promoting a CAF-like phenotype characterized by an increased expression of FAP, α-SMA, and elevated secretion of IL-6, IL-8, and TGF-β." (PMID 40940809, 2025). "These MCM2-activated CAF-like cells enhanced liposarcoma proliferation, migration, and invasion." (PMID 40940809, 2025). "Overall, MCM2 drives CAF-like activation and contributes to liposarcoma progression and chemoresistance, suggesting it as a potential therapeutic target." (PMID 40940809, 2025). "In liposarcoma, NIP7, RPL10L, and MCM2 are significantly associated with long-term no recurrence survival rate." (PMID 34712323, 2021).
metastatic disease (2 papers, 2015 to 2023). "CDC6, DHFR, E2F1, H2AFZ, MCM2, GUSB and B2M were significantly higher in patients with metastatic disease than in healthy controls, and CDC6, DHFR and E2F1 were significantly higher in metastatic patients than in localized patients." (PMID 37046768, 2023). "In our study, Ki-67, MCM2 and MCM3 expression levels were higher in AC than in UA and SMA, which indicate aggressive, invasive, and metastatic neoplasm." (PMID 26823641, 2015).
multiple myeloma (2 papers, 2021). "Increased expression of MCM2 was found to be an independent adverse prognostic factor, and MCM2 has served as a prognostic marker for multiple myeloma." (PMID 34490114, 2021).
ovarian adenocarcinoma (2 papers, 2007 to 2018). An adenocarcinoma that arises from the ovary. "In ovarian adenocarcinomas, MCM-2 and MCM-5 expression increased with increasing tumour grade, advancing stage and the presence of bulk residual disease." (PMID 17940502, 2007). "Similarly, the labeling indices of MCM2 and MCM5 proteins of ovarian adenocarcinomas were associated with adverse patient outcomes in univariate and multivariate analyses." (PMID 29963273, 2018). "In conclusion, MCM-2 and MCM-5 proteins appear to be promising as prognostic markers in patients with ovarian adenocarcinomas." (PMID 17940502, 2007). "In conclusion, in the present study, we have investigated for the first time MCM-2 and MCM-5 expression in LMP tumours and ovarian adenocarcinomas in relation with clinicopathologic parameters, cell cycle modulators and patients’ survival." (PMID 17940502, 2007). "A main scope of our study was to investigate for the first time the prognostic relevance of MCM-2 and MCM-5 expression in ovarian adenocarcinomas." (PMID 17940502, 2007). "Therefore, MCM2 and MCM5 proteins are promising prognostic markers in patients with ovarian adenocarcinoma." (PMID 29963273, 2018).
sensorineural hearing loss (2 papers, 2015 to 2021). "The role of MCM proteins in cilia formation is also consistent with familial sensorineural hearing loss with MCM2 defects and adrenal disease in MCM4 NKD patients." (PMID 33477564, 2021). "In this study, a heterozygous missense c.130C>T variant in MCM2 was identified in a Chinese family with nonsyndromic, postlingual, and progressive sensorineural hearing loss." (PMID 26196677, 2015).
serous cystadenoma (2 papers, 2004 to 2007). A serous neoplasm in which the cysts and papillae are lined by a single layer of cells without atypia, architectural complexity or invasion. "Our findings support and expand the previously reported increase of MCM-2 expression during the progression from normal ovary through serous cystadenoma and serous borderline tumours to serous cystadenocarcinomas." (PMID 17940502, 2007). "We observed an increase in the LIs of Mcm-2, cyclins D1, A and B1 and phosphohistone H3 in ovarian serous cystadenocarcinomas compared to borderline serous tumours, serous cystadenomas and normal ovary." (PMID 15083189, 2004).
adenoid cystic carcinoma (1 paper, 2011). A malignant tumor arising from the epithelial cells. "Adenoid cystic carcinoma demonstrated high value of MCM2 expression; this finding gives an impression of the high proliferative power of ADCC." (PMID 21943228, 2011). "The level of MCM2 expression can be used in the differential diagnosis of adenoid cystic carcinoma and polymorphous low grade adenocarcinoma." (PMID 21943228, 2011).
alcohol (1 paper, 2013). "The presence of Mcm-2, which is present throughout the cell cycle, in both regenerating liver and ALD shows the replicative response of hepatocyte to acute ischaemia and alcohol-related insult, respectively." (PMID 24086266, 2013).
Alexander disease (1 paper, 2007). Alexander disease (AxD) is a rare neurodegenerative disorder of the astrocytes comprised of two clinical forms: AxD Type I and Type II manifesting with various degrees of macrocephaly, spasticity, ataxia and seizures and leading to psychomotor regression and death. "Other predictions include involvement of MCM2 and MCM3 in hypolactasia, S100B in Alexander disease, and CFHL1 in chronic hypocomplementemic nephropathy." (PMID 18042286, 2007).
Atypical Meningioma (1 paper, 2023). A WHO grade II meningioma characterized by the presence of an increased mitotic activity or at least three of the following morphologic features: small cells, high cellularity, prominent nucleoli, lack of architectural pattern, and necrosis. "We studied 55 primary atypical meningiomas, treated with gross total resection and no adjuvant therapies, to assess whether ACADL and MCM2 immuno-expression may identify patients at higher recurrence risk, thus requiring adjuvant treatments." (PMID 37014425, 2023).
Autosomal Dominant Nonsyndromic Deafness (1 paper, 2015). "Therefore, we considered that this novel missense variant in MCM2 was responsible for the autosomal dominant deafness in this pedigree." (PMID 26196677, 2015).
B-cell lymphomas (1 paper, 2016). "In addition, elevated MCM2 expression in the high growth fraction of B-cell lymphomas has been reported." (PMID 27780919, 2016).
basal cell carcinoma (1 paper, 2022). A carcinoma involving the basal cells. "The mean labeling indices of geminin, ki67 and MCM2 in our basal cell carcinomas were 12.09 ± 7.49, 32.97 ± 20.51 and 88.23 ± 12.17 respectively." (PMID 32972865, 2022).
benign thyroid tumors (1 paper, 2023). "In conclusion, immunohistochemical staining for Metallothionein, E-Cadherin and MCM2 significantly distinguished between benign thyroid tumors and PTC." (PMID 36676734, 2023).
cerebrovascular disease (1 paper, 2023). "Our study suggests that the miR-212-3p/MCM2 axis may have therapeutic potential in treating BBB disorder-related cerebrovascular disease." (PMID 36769104, 2023). "Taken together, these results suggest that the miR-212-3p/MCM2 axis plays an important role in BMECs under hypoxia and provide a potential target for the treatment of BBB disorder-related cerebrovascular disease." (PMID 36769104, 2023).
ciliopathy (1 paper, 2019). A genetic disorder of the cellular cilia or the cilia anchoring structures, the basal bodies, or of ciliary function. "Zebrafish depleted of MCM2 develop ciliopathy-phenotypes including microcephaly and aberrant heart looping due to malformed cilia." (PMID 30329080, 2019).
co-infection (1 paper, 2012). "However, as we and others have shown, co-infection by HPV and HIV-1 results in marked cytokine profile changes in the lamina propria of the cervix which could translate into decreased MCM-2 expression in the overlying CIN cells." (PMID 22493662, 2012).
cyst (1 paper, 2022). A sac-like closed membranous structure that may be empty or contain fluid or amorphous material. "To evaluate Notch3’s effect on proliferation and cyst formation, we measured proliferation using PCNA and MCM-2." (PMID 35055068, 2022).
diffuse astrocytoma (1 paper, 2013). A low-grade (WHO grade II) astrocytic neoplasm. "The aim of this study was to investigate the prognostic role of Mcm2 expression in a series of diffuse astrocytomas WHO grade II and to correlate it with histopathological features, mitoses, and Ki67/MIB-1 immunostaining." (PMID 23618321, 2013). "This study was designed to evaluate the prognostic significance of the proliferation marker Mcm2 in a series of diffuse astrocytoma WHO grade II with thorough follow-up, and to compare its expression with histopathological features, mitoses, as well as Ki67/MIB-1 immunostaining." (PMID 23618321, 2013). "This study was designed to investigate the prognostic significance of the proliferative marker Mcm2 (minichromosome maintenance protein 2) in diffuse astrocytomas WHO grade II and correlate the findings with histopathology, mitoses, and Ki67/MIB-1 immunostaining." (PMID 23618321, 2013).
dissection (1 paper, 2021). The separation and isolation of tissues for surgical purposes, or for the analysis or study of their structures. "In summary, our studies showed that MCM2, MCM4, and MCM10 play an important role in aortic dissection and the expression of MCMs was inhibited by atorvastatin treatment." (PMID 33803192, 2021).
esophageal tumors (1 paper, 2020). "Human papillomavirus positivity in combination with pRb, CD1, MCM2, and Ki-67 was associated with a survival benefit in esophageal tumors." (PMID 32058552, 2020). "None of the biomarkers tested independently had any association with disease-free survival: pRb, CD1, MCM2, and Ki-67 stratified by human papillomavirus status was associated with a survival benefit in esophageal tumors." (PMID 32058552, 2020). "Moreover, on multivariable analysis, HPV-positive/high-expression MCM2 esophageal tumors had a superior disease-free survival as compared with HPV-negative/high-expression MCM2." (PMID 32058552, 2020).
Ewing sarcoma (1 paper, 2025). A small round cell tumor that lacks morphologic, immunohistochemical, and electron microscopic evidence of neuroectodermal differentiation. "Further supporting a critical role for the MCM2–7 and the pre-RC in Ewing sarcoma tumors, the Dbf4-dependent Cdc7 kinase (DDK), which initiates replisome assembly by phosphorylating the N-terminal tails of Mcm2, Mcm4, and Mcm6, was recently identified as a target in Ewing sarcoma tumors." (PMID 40478628, 2025).
Fibroadenoma (1 paper, 2011). A benign tumor of the breast characterized by the presence of stromal and epithelial elements. "In another recent study of benign breast tissues from 30 patients who underwent lumpectomy for fibrocystic changes, ductal hyperplasia, and fibroadenomas, the overall MCM2 labeling index was from 0% to 12%." (PMID 21785684, 2011).
ganglioglioma (1 paper, 2018). A well differentiated, slow growing neuroepithelial neoplasm composed of neoplastic, mature ganglion cells and neoplastic glial cells. "Dysmorphic cells in ganglioglioma infrequently labelled with MCM2 in contrast to MVNT." (PMID 28833756, 2018).
head and neck squamous cell carcinoma (1 paper, 2023). A squamous cell carcinoma that arises from any of the following anatomic sites: lip and oral cavity, nasal cavity, paranasal sinuses, pharynx, larynx, and salivary glands. "Five genes (KNTC1, MCM2, CKAP2, RACGAP1, CCNB1) were found to be associated with head and neck squamous cell carcinoma, necrosis, inflammation and hepatomegaly." (PMID 37480569, 2023). "CTD analysis showed that KNTC1, MCM2, CKAP2, RACGAP1, CCNB1 were associated with head and neck squamous cell carcinoma, necrosis, inflammation and hepatomegaly." (PMID 37480569, 2023).
infertile (1 paper, 2022). "Additionally, aberrant overexpression of MCM2 and MCM6 may cause abnormal epithelial proliferation and nonreceptive endometrium in infertile women with endometriosis." (PMID 35232969, 2022). "However, aberrant overexpression of MCM2 and MCM6 may cause abnormal epithelial proliferation and nonreceptive endometrium in infertile women with endometriosis." (PMID 35232969, 2022).
large cell lung carcinoma (1 paper, 2021). "Meanwhile, analyzed with the same Hou’s database, the mRNA level of MCM2 was upregulated in large cell lung carcinoma and LUAD patients with a fold change of 5.129 and 3.25, respectively." (PMID 33936158, 2021).
melanocytic neoplasm (1 paper, 2021). "The different expression levels of MCM2 in melanocytic neoplasms potentially provide a useful tool to distinguish benign melanocytic lesions from malignant melanocytic lesions." (PMID 34490114, 2021).
mucoepidermoid carcinoma (1 paper, 2014). A carcinoma morphologically characterized the presence of cuboidal mucous cells, goblet-like mucous cells, squamoid cells, cystic changes, and a fibrotic stromal formation. "Recent study has demonstrated that decreased expression of maspin (mammary serine protease inhibitor) and marked increase of MCM2 (minichromosome maintance-2) expression support the diagnosis of high-grade mucoepidermoid carcinoma." (PMID 24475740, 2014).
myeloid neoplasm (1 paper, 2020). Proliferation of myeloid cells originating from a primitive stem cell. "As mentioned in the present manuscript, hosts with higher expression of MCM2 might be more susceptible to MDS‐type myeloid neoplasms while MCM2‐low hosts have a higher risk of developing AML or MPN when genetic mutations occur in hematopoietic stem cells." (PMID 31709722, 2020).
Myoepithelial carcinoma (1 paper, 2011). "Myoepithelial carcinoma showed the smallest value of maspin expression, and high value of MCM2 expression." (PMID 21943228, 2011).
nasopharyngeal carcinoma (1 paper, 2022). A carcinoma arising from the nasopharyngeal epithelium. "In our study, MCM complex subunits (MCM2–7) overexpression was found as a poor prognostic factor associated with survival outcomes for patients with nasopharyngeal cancer." (PMID 34144903, 2022). "Although there is no study in the literature examining the prognostic effect of MCM2 expression in nasopharyngeal cancer, the results of our study are compatible with the literature in that the results are more aggressive in patients with high MCM2 expression." (PMID 34144903, 2022).
odontogenic cyst (1 paper, 2012). A cyst in the jaw that arises from tissues of tooth development. "The mean Ki-67 and MCM-2 expressions in odontogenic cysts were 12,17 ± 4,49 and 19,17 ± 3,76 in RCs, 7,43 ± 3,99 and 7 ± 4,25 in DCs, and 16 ± 13,46 and 15,43 ± 14,04 in KCOTs, respectively." (PMID 22778705, 2012). "The mean Ki-67 and MCM-2 expressions were found 9, 64 ± 5, 99 and 6, 34 ± 3, 81 in DF, 11, 85 ± 9, 01 and 13, 6 ± 9, 94 in odontogenic cysts, respectively." (PMID 22778705, 2012). "The aim of this study was to investigate whether there is any association between inflammation and the expression of markers of cell cycle entry (Ki-67 and MCM-2) in dental follicle (DF) of asymptomatic impacted teeth and odontogenic cysts." (PMID 22778705, 2012). "Thus, the aim of this study was to investigate whether there is any association between inflammation and the expression of markers of cell cycle entry (Ki-67 and MCM-2) in dental follicle (DF) of asymptomatic impacted teeth and odontogenic cysts." (PMID 22778705, 2012).
oesophageal cancer (1 paper, 2004). "The elevated levels of the Mcm5 DNA replication licensing protein found in gastric aspirates from patients with oesophageal cancer is consistent with our previous immunohistochemical findings demonstrating aberrant expression of Mcm2 and Mcm5 proteins in dysplastic and malignant oesophageal lesions." (PMID 15266314, 2004).
Pan (1 paper, 2023). "MCM2 was significantly upregulated in copy number in many tumors, which was consistent with its widely upregulated expression in Pan-cancer." (PMID 37723560, 2023).
pancreatic adenocarcinoma (1 paper, 2018). "In this study, we found that MCM2 was increased along with the tumor differentiation grades, which further demonstrated the crucial role of MCM2 in cell differentiation of pancreatic adenocarcinoma." (PMID 29596435, 2018). "Significantly, we also found the diagnosis and prognosis value of MCM2 in pancreatic adenocarcinoma." (PMID 29596435, 2018). "Finally, 8 differentially expressed genes (ERLIN1, HMGA2, FAM110B, EGFR, MCM2, BCL2L1, E2F1 and RAC1) were considered to be significantly negatively associated with survival (P < 0.05) time of pancreatic adenocarcinoma patients." (PMID 29596435, 2018). "Among these genes, JUB, ERLIN1, FAM110B, MCM2 and BCL2L1 also had a diagnosis value for pancreatic adenocarcinoma." (PMID 29596435, 2018).
prostate adenocarcinoma (1 paper, 2021). "High levels of MCM2/3/4/6 were significantly enriched in human NEPC compared to castration-resistant prostate adenocarcinoma." (PMID 34172788, 2021). "Four proteins of the MCM2-7 complex, including MCM2/3/4/6, were identified as highly elevated in the TD-NEPC model when compared to LNCaP prostate adenocarcinoma xenografts." (PMID 34172788, 2021). "In addition, MCM2/3/4/6 protein levels were also notably elevated in the NEPC cell line models TD-NEPC and NCI-H660 compared to prostate adenocarcinoma cell lines." (PMID 34172788, 2021).
rectal adenocarcinoma (1 paper, 2020). "Moreover, MCM2 was 2.083- and 2.199-fold higher in colon and rectal adenocarcinoma samples respectively compared with normal tissues." (PMID 32597491, 2020).
renal carcinoma (1 paper, 2022). A carcinoma arising from the epithelium of the renal parenchyma or the renal pelvis. "In addition, Ki-67 can be used in combination with other markers such as MCM-2, survivin, B7-H1, geminin, carbonic anhydrase, IX, gelsolin, MIB-1, and phosphorylated S6 protein, and the interaction between white (pS6) and vimentin affects the prognosis of renal cancer." (PMID 35741311, 2022).
salivary duct carcinoma (1 paper, 2011). An aggressive, high grade adenocarcinoma that arises from the salivary glands. "Salivary duct carcinoma revealed the highest value of MCM2 expression and reduced maspin expression; this finding confirms the high grade behavior of this tumor." (PMID 21943228, 2011).